NLRP3 (NLR family pyrin domain containing 3)
Diseases named in the same sentence as NLRP3 in open-access papers (continued):
Sharing a sentence is not in itself a finding about the gene and the disease.
endometritis (continued). "Here, we utilized porcine endometritis models and lipopolysaccharide (LPS)-treated Ang knockout (Ang−/−) mice to investigate the function of Ang in NLRP3 inflammasome activation." (PMID 40723465, 2025). "For example, miR-223 alleviates inflammation by targeting NLRP3, and miR-148a negatively regulates endometritis via TLR4 signaling." (PMID 40298790, 2025). "In a porcine model of endometritis, NLRP3 inflammasome activation was accompanied by significantly increased Ang protein expression." (PMID 40723465, 2025). "Collectively, these findings indicate that Ang alleviates LPS-induced endometritis by suppressing NLRP3 inflammasome activation and promotes endometrial epithelial cell proliferation during inflammation." (PMID 40723465, 2025). "Taken together, these findings emphasize the protective effect of PU on endometritis by regulating the P2X7 receptor/NLRP3 signalling pathway and inhibiting ferroptosis." (PMID 39042561, 2024). "Our study results indicated that PU can reverse the increased expression of NLRP3, ASC, caspase‐1 and P2X7 proteins caused by endometritis, indicating that PU can inhibit the occurrence of endometritis through P2X7 receptor/NLRP3 signalling pathway." (PMID 39042561, 2024). "All these findings indicated that melatonin played a protective role in endometritis by inhibiting the activation of the NLRP3 inflammasome." (PMID 37570258, 2023). "Our in vivo data showed that ginsenoside Rg1 relieved endometrial fibrosis of the mouse model of LPS-induced endometritis by restraining the ROS/NLRP3 inflammasome signaling pathway." (PMID 38067074, 2023). "Previous studies have demonstrated that the total flavonoids from Clinopodium chinense alleviate LPS-induced endometritis by inhibiting NLRP3-mediated apoptosis." (PMID 37570258, 2023). "MiR-223 targets to inhibit the activation of NLRP3 inflammasome in bovine endometritis, which is the mechanism of its possible treatment of endometritis." (PMID 37570258, 2023). "NLRP3, responsible for the maturation and secretion of IL-1β, has been proven to be related to the development of endometritis in dairy cows." (PMID 37570258, 2023). "Qualitative and quantitative analysis of major pyroptosis-related proteins (caspase-1, caspase-4, ASC, GSDMD-N, and NLRP3) in endometrial tissues showed that pyroptosis occurred in endometrial tissues of cows with endometritis." (PMID 36430491, 2022). "In a mouse LPS-induced endometritis model, melatonin reverses neutrophil infiltration and the rise in ROS, ER stress, and protein levels of NLRP3 inflammasome components in endometrial tissue through inhibiting NF-κB and TXNIP and upregulating AMPK." (PMID 34202842, 2021). "Overexpression of miR-223 can reduce the activation level of NOD-like receptor (NLRP3) to attenuate LPS-induced endometritis." (PMID 33718475, 2021). "As previously reported, we found TLR2−/−47, MyD88−/−48, NOD1−/−49, NOD2−/−, GBP−/− knockout mice developed severe endometritis, excluding them in the activation of NLRP3 inflammasome." (PMID 34526512, 2021). "Emerging evidence suggests that NLRP3 inflammasome activation occurs in endometritis cells, while inhibiting NLRP3 inflammasomes generates a significant ameliorative role in the pathological process of endometritis." (PMID 32595419, 2020). "Collectively, these findings indicate that A20 may serve as a promising therapeutic target for bovine endometritis and other NLRP3 inflammasome-related disorders." (PMID 41463800, 2025). "Research demonstrates that nucleotide-binding oligomerization domain-like receptor family, pyrin domain-containing 3 (NLRP3) inflammasome activation occurs in endometritis, leading to extracellular secretion of pro-inflammatory cytokines IL-1β and IL-18 and subsequent pyroptosis." (PMID 40723465, 2025). "Additionally, our previous findings also indicated that bile acid preconditioning alleviates LPS-induced endometritis in mice by suppressing NLRP3 inflammasome activation." (PMID 40723465, 2025).
endometritis (continued). "PU can alleviate endometritis by inhibiting ferroptosis via P2X7 receptor/NLRP3 signalling pathway." (PMID 39042561, 2024). "Melatonin improved mouse endometritis by constraining the level of NLRP3 activation." (PMID 36106027, 2022). "Melatonin downregulates ER-induced TXNIP/NLRP3 pathway in LPS-induced endometritis." (PMID 34202842, 2021). "These NLRP3 functions could be explored to understand bovine endometritis pathogenesis with exposure to the PAMPs." (PMID 34071093, 2021). "NLRP3 levels are reported to be increased in uterine tissue in endometritis models." (PMID 34202842, 2021). "We found CT135 activates the NLRP3 inflammasome through TLR2/MyD88 signaling pathway as a pathogenic strategy to evade neutrophil host defense, however, this strategy conjointly caused NLRP3 dependent macrophage-associated endometritis." (PMID 34526512, 2021). "Conjointly, this pathogenic strategy drives submucosal macrophage-associated endometritis through ATP-induced NLRP3 inflammasome activation independent of chlamydial infection." (PMID 34526512, 2021). "Our results also showed an increased level of NLRP3 during endometritis in dairy cows." (PMID 30186287, 2018). "Our results revealed that activation of NF-κB in LPS-induced BEND cells in vitro and endometritis in vivo promoted the transcription of miR-223 and thus inhibited the activation of inflammatory mediators of NLRP3-mediated IL-1β production to protect the uterus from inflammatory damage." (PMID 30186287, 2018). "With regard to the impact of Ang deficiency on endometritis, our investigation was limited to the mice and lacked in vitro cellular-level experiments to examine the mechanism of Ang protein in the activation of NLRP3 inflammasome." (PMID 40723465, 2025). "Therefore, targeting NLRP3 inflammasome inhibition could represent a promising therapeutic strategy for treating endometritis." (PMID 40723465, 2025). "In addition, melatonin has been found to inhibit endoplasmic reticulum (ER) stress-mediated thioredoxin interacting protein (TXNIP)/NLRP3 inflammasome activation via adenosine monophosphate-activated protein kinase (AMPK) regulation in LPS-induced endometritis." (PMID 40723465, 2025). "Thus, the removal of damaged mitochondria by autophagy to inhibit the excessive activation of NLRP3 inflammation may be a strategy for the amelioration of endometritis." (PMID 37570258, 2023). "Therefore, inhibition of NLRP3 inflammasome activation may be a target for the treatment of endometritis." (PMID 37570258, 2023). "Hence, inhibition of NLRP3-caspase-1-mediated IL-1β production may be a possible target for ameliorating endometritis." (PMID 37570258, 2023). "In summary, our study highlights that miR-223 serves both to constrain the level of NLRP3 activation and to act as a protective factor in the inflammatory response and thus provides a future novel therapeutic modality for active flares in cow endometritis and other inflammatory diseases." (PMID 30186287, 2018). "Western blot analysis demonstrated a significant elevation in the expression of NLRP3, pro-Caspase1, cleaved-Caspase1, and ASC proteins in cases of porcine endometritis." (PMID 40723465, 2025). "However, it is still unclear whether P2X7/NLRP3 signalling pathway can regulate endometritis." (PMID 39042561, 2024). "Moreover, the activation of the NLRP3 inflammasome aggravates the degree of inflammatory infiltration in gynecological diseases such as endometritis and pelvic inflammatory disease, which indicates that therapeutic interventions via the NLRP3 inflammasome may be a novel strategy for treating PD." (PMID 32595419, 2020). "Thus, in the present study, we assume that NF-κB-induced upregulated miR-223 during endometritis may serve as a “protective factor” that inhibits the activation of the NLRP3 inflammasome, which may also a potential therapeutic target for the treatment of endometritis in dairy cows and other mammals." (PMID 30186287, 2018).
endometritis (continued). "Therefore, we measured caspase-1/4, ASC, NLRP3, and GSDMD-N levels to determine whether pyroptosis occurs in endometritis." (PMID 36430491, 2022).
Hypercholesterolemia (21 papers, 2014 to 2026). An increased concentration of cholesterol in the blood. "PCAD progression is also influenced by inflammatory pathways (e.g. NLRP3 inflammasome activation) and genetic predispositions (e.g. 9p21 locus polymorphisms, familial hypercholesterolemia)." (PMID 41614676, 2026). "IL-1β precursor is activated into a mature cytokine by triggering the caspase/NLRP3-inflammasome axis secondary to intracellular or extracellular danger-associated signals such as hypercholesterolemia; a detected feature of hypothyroidism." (PMID 40672362, 2025). "Our findings may offer novel therapeutic insights into targeting ASM-ceramide-MR redox signaling or TXNIP to suppress the activation of endothelial NLRP3 inflammasomes, thereby preventing and treating vasculopathy associated with hypercholesterolemia." (PMID 36252682, 2022). "Moreover, endothelial dysfuction is attenuated by NLRP3 gene deficiency in hypercholesterolemia mice." (PMID 32010692, 2019). "Hypercholesterolemia has been found to trigger the activation of the NLRP3 inflammasome, which leads to a chronic state of inflammation." (PMID 36926027, 2023). "Together, these data suggest that EC-specific Smpd1 gene overexpression enhances endothelial NLRP3 inflammasome formation and activation in the carotid arteries of mice during hypercholesterolemia." (PMID 36252682, 2022). "The present study revealed the critical contribution of endothelial ASM-ceramide MR redox signaling pathway to hypercholesterolemia-induced NLRP3 inflammasome activation and neointimal hyperplasia." (PMID 36252682, 2022). "We conclude that ceramide from ASM plays a critical role in NLRP3 inflammasome activation during hypercholesterolemia via MR redox signaling platforms to produce superoxide, which leads to TXNIP dissociation." (PMID 36252682, 2022). "Our results agree with earlier findings showing hypercholesterolemia triggers trained immunity in hematopoietic cells via activation of Nlrp3-inflammasome." (PMID 35372506, 2022). "Together, these results suggest that NLRP3 inflammasome-dependent IL-1β production during hypercholesterolemia promotes VSMC phenotype transition to synthetic status via EV machinery, which is controlled by lysosomal AC activity." (PMID 33409276, 2020). "Upon exposure to pathogens, these cells were primed allowing for a more robust inflammatory response which was partially hypercholesterolemia and NLRP3-dependent." (PMID 32774894, 2020). "In this study, hypercholesterolemia increased NLRP3 and TNF-α, which is one of the most potent inducers of NF-κB." (PMID 33050202, 2020). "The present study indicated that endothelial NLRP3 inflammasome activation is critically involved in reversing endothelial EV-induced VSMC phenotype transition by hypercholesterolemia stimulation." (PMID 33409276, 2020). "Recent study demonstrated that ASM and ceramide contribute to NLRP3 inflammasome formation and activation in hypercholesterolemia mice." (PMID 32010692, 2019). "Targeting EV-mediated release of NLRP3 inflammasome products regulated by AC may represent a novel strategy for the prevention and treatment of vasculopathy with hypercholesterolemia." (PMID 33409276, 2020). "Additionally, more investigations are needed to elucidate how ox-LDL accumulation decreases SCGN expression and whether the SCGN-regulated NLRP3/Caspase-1 pathway is impaired in patients with hypercholesterolemia." (PMID 39068218, 2024). "Our present findings suggest that these distinct mechanisms of JNK activation converge on BRCC3 and NLRP3 in hypercholesterolemia and TET2 CH resulting in synergistic NLRP3 activation." (PMID 38522750, 2024). "CH reduces hypercholesterolemia-mediated atherosclerosis via modulating the inflammatory genes expression including TNF-α, toll-like receptors (TLR4), IL-17, and NLRP3 in the intestine and aorta compared with hypercholesterolemia control rats." (PMID 38966181, 2024).
Hypercholesterolemia (continued). "Our results demonstrated that EC-specific overexpression of the Smpd1 gene enhanced hypercholesterolemia-induced neointimal formation, which was accompanied by augmented ASM-ceramide-MR redox signaling and NLRP3 inflammasome formation and activation in the arterial endothelium." (PMID 36252682, 2022). "Together, these results from the ASM overexpression studies provide direct evidence that hypercholesterolemia or cholesterol stimulation instigates the ASM-ceramide pathway to induce MR redox signaling platform formation in ECs and thereby trigger endothelial NLRP3 inflammasomes." (PMID 36252682, 2022).
malaria (21 papers, 2009 to 2025). Malaria is a serious and sometimes fatal disease caused by a parasite that commonly infects a certain type of mosquito which feeds on humans. "In malaria, on the other hand, NLRP3 and its associated cytokines have an immunopathologic role." (PMID 40586570, 2025). "Many studies aim to comprehend the effects of NLRP3 deficiency during malaria." (PMID 38623843, 2024). "Corroborating this hypothesis, we showed that IL-1β- and NLRP3- deficient mice showed a better survival than wild type mice in murine experimental model of malaria." (PMID 19696895, 2009). "NLRP3 has been targeted in many malaria vaccines, such as QS-21, a soluble saponin adjuvant that induces IL-1β/IL-18 production and promotes Th1 responses in macrophages and dendritic cells." (PMID 38623843, 2024). "The NLRP3 inflammasome is activated in the placentas of pregnant women who have malaria, and monocytes from malaria patients express NLRP3 inflammasome component proteins." (PMID 37141324, 2023). "We have previously shown that AIM2 and NLRP3 inflammasomes, as well as caspase-1, are activated in monocytes from malaria patients." (PMID 32929083, 2020). "The higher amount of MyD88-IRF7 dependent type I IFN cytokines in pDCs of Il1r1−/−, Aim2−/−, Nlrp3−/−, and Casp1−/− mice at the early stage of YM infection facilitates anti-malaria adaptive immune response." (PMID 30470758, 2018). "Recent studies show that malaria hemozoin can activate the NLRP3 inflammasome in experimental cerebral malaria." (PMID 30470758, 2018). "Mechanistically, we show that AIM2 and NLRP3 inflammasome activation by YM infection produces IL-1β in pDCs and potentially many other cell types, depending upon exposure of malaria." (PMID 30470758, 2018). "Here we provide the first demonstration that the malaria pigment hemozoin (Hz) can also activate the NLRP3 inflammasome." (PMID 19696895, 2009). "NLRP3 activation may also induce neuroinflammation during cerebral malaria (CM), a type of malaria with high mortality and affecting approximately 3 million individuals each year." (PMID 38623843, 2024). "However, examining the role of NLRP3 activation in vaccine development for malaria is beyond the scope of this review." (PMID 38623843, 2024). "Developing vaccination candidates against malaria that target the NLRP3 pathway, may lead to better infection control." (PMID 38623843, 2024). "Thus, the role of monocytes, and in particular the activation of the NLRP3 inflammasome and Il-1β generation, in P. falciparum infection and pathogenesis of malaria is still debatable." (PMID 37141324, 2023). "Furthermore, it was demonstrated that monocytes from febrile malaria patients express high levels of NLRP3, NLRP12, and AIM2 inflammasome specks, as well as active caspase-118,19." (PMID 32929083, 2020). "Therefore, P. chabaudi malaria induces NLRP3 inflammasome-independent IL-1α production in the liver." (PMID 31110285, 2019). "Furthermore, we observed the presence of inflammasome complexes in monocytes from malaria patients containing either NLRP3 or NLRP12 pyroptosomes." (PMID 24453977, 2014). "We conclude that NLRP12/NLRP3-dependent activation of caspase-1 is likely to be a key event in mediating systemic production of IL-1β and hypersensitivity to secondary bacterial infection during malaria." (PMID 24453977, 2014). "We also observed decreased expression of NLRP3 after malaria relative to baseline." (PMID 24743880, 2014). "High concentrations of immunocomplexes containing parasite DNA induce the AIM2 and NLRP3 inflammasome assembly, caspase-1 activation and IL-1β secretion in monocytes from infected patients, thereby stimulating systemic inflammation during acute malaria episodes." (PMID 39548522, 2024). "Furthermore, the absence of NLRP3 or IL-1β augmented survival to malaria caused by P. chabaudi adami DS." (PMID 19696895, 2009).
malaria (continued). "Taken together, these results suggest that malaria gDNA, RNA and hemozoin activate inflammasome through AIM2 and NLRP3 signaling during YM infection." (PMID 30470758, 2018). "During malaria, AIM2 and NLRP3-induced CASP1-dependent inflammasome signaling induces the release of IL-1β in pDCs and activates IL-1 signaling, which induces negative regulator SOCS1 in a MyD88-TRAF3-IRF3-dependent manner and inhibits MyD88-IRF7-dependent type I IFN signaling in pDCs." (PMID 36214572, 2022). "Furthermore, infected erythrocytes can activate both NLRP3 and AIM2 inflammasomes during malaria in vitro stimulation." (PMID 30470758, 2018). "Although AIM2 and NLRP3 have been identified as sensors of malaria gDNA and hemozoin in vitro, their in vivo function has not been reported." (PMID 30470758, 2018). "Notably, we notice an in vivo assembly of NLRP3 and NLRP12 specks and ASC oligomerization in febrile malaria patients." (PMID 24453977, 2014). "Conversely, the absence of NLRP3 or IL-1β resulted in increased survival of the malaria strain P. chabaudi adami DS, indicating that NLRP3 promotes malaria pathology." (PMID 24098823, 2013). "Nlrp3 can however influence experimental cerebral malaria independently of caspase-1 and IL-1β, suggesting a non-classical role for Nlrp3 in malaria immunopathology." (PMID 23405174, 2013). "Second, heme, a marker of hemolysis or extensive cell damage, activates the NLRP3 inflammasome and promotes IL-1β synthesis in macrophages by inducing Syk and NADPH oxidase-2 activation, mitochondrial ROS production, and potassium efflux, which play critical roles in malaria pathogenesis." (PMID 39548522, 2024). "However, in a human and murine study of infection using peripheral blood mononuclear cells, malaria induced the assembly of ASC, NLRP3 and NLRP12 inflammasomes jointly and promoted cleavage of procaspase-1, leading to IL-1β and hypersensitivity to bacterial superinfection." (PMID 38343435, 2023).